NUPR1 (nuclear protein 1, transcriptional regulator)
Diseases named in the same sentence as NUPR1 in open-access papers (continued):
Sharing a sentence is not in itself a finding about the gene and the disease.
hepatocellular carcinoma (16 papers, 2018 to 2025). A malignant tumor that arises from hepatocytes. "A metabolism-associated role of NUPR1 was previously suggested in hepatocellular carcinoma, in which expression of Nupr1 is induced in response to the mitochondrial malfunction, and consequently, NUPR1 overexpression favors cancer progression." (PMID 30451898, 2018). "Silencing NUPR1 hampered autophagic flux and promoted apoptosis, thereby increasing the sensitivity of hepatocellular carcinoma cell to sorafenib." (PMID 37305393, 2023). "Targeting the NUPR1 with a strong inhibitor has been reported to treat pancreatic adenocarcinoma and hepatocellular carcinoma." (PMID 36468653, 2023). "Overall, we identified a novel function of NUPR1 in regulating hepatocellular carcinoma progression via modulation of SREBP1-mediated de novo lipogenesis." (PMID 36307402, 2022). "We also found that hepatocellular cancer cells with higher NUPR1 expression levels exhibited a more invasive phenotype." (PMID 36307402, 2022). "We found that NUPR1 was significantly upregulated in human hepatocellular carcinoma cells compared with normal hepatocytes from LIHC patients in TCGA cohorts and our patients." (PMID 36307402, 2022). "More importantly, we demonstrated that high NUPR1-expressing hepatocellular cancer cells showed a strong proliferative ability in vitro and in vivo, while NUPR1 knockdown inhibited tumor growth in the subcutaneous xenograft model." (PMID 36307402, 2022). "The radiotherapeutic resistance of hepatocellular carcinoma cells could be enhanced by NUPR1 (nuclear protein 1) expression." (PMID 40847302, 2025). "In addition, NUPR1 knockdown significantly inhibited hepatocellular carcinoma cell proliferation and migration in vitro and hindered tumorigenesis in vivo." (PMID 36307402, 2022). "A previous study reported that NUPR1 mediated sorafenib resistance in hepatocellular carcinoma." (PMID 34030133, 2021). "Targeting NUPR1-SREBP1/FASN pathway may be a therapeutic alternative for hepatocellular carcinoma." (PMID 36307402, 2022). "However, little is currently known on the role of NUPR1 in hepatocellular carcinoma." (PMID 36307402, 2022). "The expression level of NUPR1 was significantly correlated with vascular infiltration and advanced TNM staging, and its small-molecule inhibitor, ZZW-115, significantly inhibited hepatocellular carcinoma progression." (PMID 40649911, 2025). "Targeting the NUPR1 with the strong inhibitor ZZW‐115 is considered as a new strategy to treat pancreatic adenocarcinoma and hepatocellular carcinoma." (PMID 36468653, 2023). "The role of NUPR1 has also been examined in hepatocellular carcinoma (HCC)." (PMID 35883598, 2022). "The present study demonstrated that NUPR1 promoted HCC cells growth and migration contributing to hepatocellular cancer progression, consistent with the published literature." (PMID 36307402, 2022). "The circPIAS1/NUPR1 axis suppresses ferroptosis activity in hepatocellular carcinoma (HCC) cells by upregulating FTH1, thereby accelerating HCC progression." (PMID 40725394, 2025). "Conversely, circPIAS1 has been found to suppress ferroptosis by competitively binding to miR-455-3p, thereby upregulating Nuclear Protein 1 (NUPR1), which facilitates the growth and metastatic potential of hepatocellular carcinoma (HCC)." (PMID 41213937, 2025). "CircPIAS1 promotes hepatocellular carcinoma progression by inhibiting ferroptosis through the miR-455-3p/NUPR1/FTH1 axis, with NUPR1 inhibition sensitizing HCC cells to lenvatinib." (PMID 39315094, 2024).
lung cancer (16 papers, 2016 to 2025). A malignant neoplasm involving the lung. "Therefore, this study is aimed to explore the function and underlying mechanisms of NUPR1 in lung cancer." (PMID 37854285, 2023). "Importantly, silencing of Nupr1 by tail vein injection of lentivirus encoded shRNA against Nupr1 in vivo suppressed growth of human lung cancer xenograft, suggesting that Nupr1 plays critical roles in lung cancer development." (PMID 27285315, 2016). "Analysis of publicly available scRNA‐seq datasets from patients with non‐small cell lung cancer (NSCLC) treated with immunotherapy revealed that NUPR1 was predominantly expressed in macrophages, with minimal expression observed in fibroblasts." (PMID 40305758, 2025). "In this study, we also found that several genes related to the inflammatory response, lymphocyte activation and innate immune response in the mucosa (Hp/Reg3g/Nupr1/Adam8/Cd55/Cfh/Ednrb) were upregulated in mice with EGFRL858R*PTEN-/- induced lung cancer." (PMID 38499532, 2024). "Unfortunately, the involvement of NUPR1 in lung cancer angiogenesis and related mechanisms are unclear." (PMID 37854285, 2023). "NUPR1 mRNA and protein levels in lung cancer cell lines (A549 or H1299 cells) were silenced through siRNA transfection and western blot observed its successful infection efficiency." (PMID 37854285, 2023). "In conclusion, this study shows that si-RNA-mediated knockdown of NUPR1 significantly inhibited tubule formation activity in lung cancer and suppressed the cell migration activity, thereby suppressing tumor progression." (PMID 37854285, 2023). "In this study, NUPR1 was successfully silenced in lung cancer cell lines (A549 and H1299 cells) using si-RNA technology to investigate the effect of NUPR1 silencing on cell biological functions such as angiogenesis and migration in lung cancer." (PMID 37854285, 2023). "NUPR1 (nuclear protein 1) reduces ER stress by interacting with eIF2α and plays a tumor promoter role in lung cancer." (PMID 36110953, 2022). "Upon NUPR1 depletion, proteins such as CDKN2A, CDKN1A, and CDKN1B, which directly regulate cell cycle progression, are involved in the NUPR1-mediated autolysosomal process, which is consistent with our previous observation in lung cancer cells." (PMID 33542201, 2021). "Previously, we noticed that NUPR1 depletion results in cytoplasmic vacuolization and premature senescence in lung cancer cells." (PMID 33542201, 2021). "In the setting of NUPR1-depleted lung cancer cells, the imbalance between the increased on-rate of autophagic flux and the decreased off-rate of autolysosomal efflux impairs the autolysosomal process and results in premature senescence." (PMID 33542201, 2021). "The down-regulation of endogenous NUPR1 inhibitors can reduce lung cancer cells’ proliferation, leaving the cells in the G0/G1 cycle and leading to apoptosis." (PMID 35250903, 2021). "We also analyzed TCGA data and observed that both RNF113A and NUPR1 expression were indeed positively correlated in lung cancer." (PMID 32152280, 2020). "In this study, the effect of NUPR1 in lung cancer cell lines was estimated." (PMID 37854285, 2023). "Together, our findings suggested that inhibiting NUPR1 expression might reduce angiogenesis in lung cancer." (PMID 37854285, 2023). "Therefore, RNF113A expression prevents senescence, at least by maintaining NUPR1 expression in lung cancer cells." (PMID 32152280, 2020). "Moreover, the combination of adeno‐associated virus‐mediated NUPR1 knockdown and TFP induced premature senescence in lung cancer cells." (PMID 32810364, 2020). "Nupr1 is highly expressed in a number of cancer tissues including lung cancer." (PMID 27285315, 2016). "Further studies on the functional role of NUPR1 may lead to an improved understanding of the molecular mechanisms of lung cancer drugs, and inhibition of NUPR1 action contributing to the reduction of angiogenesis may be an effective strategy for the treatment of lung cancer." (PMID 37854285, 2023).
lung cancer (continued). "In addition, NUPR1 has been reported to contribute to the progression of lung cancer." (PMID 37854285, 2023). "The bioinformatics analysis identified five favorable prognostic MTGs (RPS6KA5, RORA, SH3BP5, NUPR1, and CD40LG) for NSCLC patients, all of which was downregulated in lung cancer tissues as compared with normal tissues." (PMID 39135791, 2024). "As result, we identified five target genes of metformin (RPS6KA5, RORA, SH3BP5, NUPR1, and CD40LG), which were significantly correlated with favorable prognosis and immune infiltration in lung cancer patients." (PMID 39135791, 2024). "MPE collected from lung cancer patients with pleural metastasis stimulated the expressions of GPX4, FTL, and NUPR1, whereas decreased the expression of ACSL4 in both A549 and H1975 cells." (PMID 37649596, 2023). "In conclusion, these findings demonstrated that NUPR1 knockdown inhibits angiogenesis in A549 and H1299 cells through IRE1/XBP1 and PERK/eIF2α/ATF4 signaling pathways, indicating that NUPR1 could represent a novel lung cancer therapeutic target." (PMID 37854285, 2023). "However, the significance of NUPR1 in lung cancer is still not entirely elucidated." (PMID 37854285, 2023).
glioblastoma (11 papers, 2019 to 2026). The most malignant astrocytic tumor (WHO grade IV). "The NUPR1 gene plays a pivotal role in the development and progression of various types of malignancies, including glioblastomas." (PMID 41596413, 2026). "In glioblastomas, NUPR1 contributes to tumor growth and resistance to conventional therapies by upregulating genes associated with mitochondrial function and antioxidant responses." (PMID 41596413, 2026). "Nupr1 is emerged as an important TF in the growth and migration of human glioblastoma cells and a potent regulator of autolysosomal dynamics via the induction of the SNARE proteins." (PMID 31959236, 2020). "NUPR1 knockdown in glioblastoma cells suppressed cell growth, by repressing ERK1/2 and p38 MAPK phosphorylation, two signaling pathways inducible by OxPAPC." (PMID 30466060, 2019). "This makes NUPR1 a potential key regulator gene in GBM, as its function could induce the metabolic adaptations that allow glioblastoma cells to thrive." (PMID 41596413, 2026). "According to TCGA dataset, overexpression of NUPR1 was observed in a variety of solid tumors including three RCC subtypes (KIRC, KICH, KIRP), glioblastoma multiforme (GBM) and lymphoma, compared to that in the corresponding normal tissues." (PMID 34030133, 2021). "Animal experiments have shown that genetic inactivation of NUPR1 suppresses different types of tumor growth, including pancreatic ductal adenocarcinoma (PDAC), hepatocarcinoma (HCC), lung adenocarcinoma, osteosarcoma, glioblastoma, cholangiocarcinoma, multiple myeloma and ovarian carcinoma." (PMID 34359572, 2021).
liver cancer (11 papers, 2016 to 2025). An epithelial or non-epithelial malignant neoplasm that arises from the liver. "To demonstrate the role of NUPR1 in the growth and migration of liver cancer cells, we overexpressed NUPR1 in MHCC-97H and SK-Hep1 cell lines and stably knocked down NUPR1 in Huh7 and SMMC-7721 cell lines based on their expression of endogenous NUPR1." (PMID 36307402, 2022). "The involvement of Ca2+ is supported by evidence of the calcium chelator BAPTA-AM significantly inhibiting elevated NUPR1 mRNA levels in liver cancer cells treated with hydrogen peroxide (H2O2)." (PMID 34359572, 2021). "Nupr1 has also been identified as a key regulator and metabolic switch in response to mitochondrial damage during liver cancer progression." (PMID 32363190, 2020). "To explore the clinical relevance of NUPR1 in liver cancer development, we analyzed the HCC microarray data sets available on the Oncomine software." (PMID 27336713, 2016). "There may be a close relationship between NUPR1 and the microenvironment in chronic hepatitis and liver cancer progression." (PMID 36307402, 2022). "Moreover, we found that NUPR1 could promote the malignant potential of liver cancer cells by facilitating nuclear translocation of the transcriptionally active form of SREBP1 and transactivating target genes FASN and SCD1, resulting in lipid accumulation." (PMID 36307402, 2022). "Collectively, NUPR1 is a promising therapeutic target of HCC and ZZW-115 has huge prospects for clinical application in treating liver cancers." (PMID 36307402, 2022). "Unlike the mechanism in liver cancer, where circPIAS1 inhibits ferroptosis through the miR-455-3p/NUPR1 axis, YBX3 directly targets SLC7A11 and destabilizes it through lysosomal degradation." (PMID 41213937, 2025). "Another study showed that NUPR1 was not activated in liver cancer cells exposed to H2O2 for a short time, but that NUPR1 protein levels increased over time accompanied by mitochondrial defects." (PMID 34359572, 2021).
pancreatic ductal adenocarcinoma (10 papers, 2014 to 2026). An infiltrating adenocarcinoma that arises from the epithelial cells of the pancreas. "In this study, we report that the combination of the NUPR1 inhibitor LZX-2-73 with sorafenib produces strong synergistic anticancer effects in various cancer cell lines as well as in primary pancreatic ductal adenocarcinoma (PDAC) organoids." (PMID 41249113, 2025). "Nuclear Protein 1 (NUPR1) is a nuclear intrinsically disordered protein (IDP) of 82 amino acids that plays an important role in pancreatic ductal adenocarcinoma (PDAC), as well as other cancers in which its genetic inactivation induces tumor growth arrest." (PMID 32780723, 2020). "Previously, we had demonstrated that Nupr1 cooperates with KrasG12D to induce pancreas intraepithelial neoplasias (PanIN) formation and pancreatic ductal adenocarcinoma development in mice." (PMID 24902898, 2014). "Notably, several of the genes affected by Cr(VI) exposure such as MLH1, RAD51, CD44, and Nupr1 are well-recognized contributors to pancreatic ductal adenocarcinoma (PDAC) development." (PMID 42039696, 2026). "Notably, NUPR1 is overexpressed in several types of cancer cells, including pancreatic ductal adenocarcinoma (PDAC) cells." (PMID 41249113, 2025). "Moreover, NUPR1 depletion in pancreatic ductal adenocarcinoma (PDAC)-derived cells, by using genetic approaches, results in cell-cycle arrest and senescence induction." (PMID 28054562, 2017). "In pancreatic ductal adenocarcinoma, an IDP, nuclear protein 1 (NUPR1), has been successfully targeted in vivo to completely arrest development of the cancer in mice." (PMID 34681018, 2021). "Such derivative compound hinders the development of pancreatic ductal adenocarcinoma (PDAC) in mice, by hampering nuclear translocation of NUPR1." (PMID 34680086, 2021). "NUPR1 is a multifunctional IDP, over-expressed and involved in pancreatic ductal adenocarcinoma (PDAC) development." (PMID 28054562, 2017). "As a member of the NUPR1/RELB/IER3 survival pathway, may provide pancreatic ductal adenocarcinoma with remarkable resistance to cell stress, such as starvation or gemcitabine treatment." (PMID 27767172, 2016).
pancreatitis (10 papers, 2010 to 2025). Inflammation of the pancreas. "Reg3 family protein expression is activated in response to pancreatitis, and family member Reg3b (also known as Pap1) specifically is implicated in maintaining acinar viability and can act downstream of Nupr1." (PMID 24788257, 2014). "However, up-regulation of NUPR1 has also been linked to the acute phase response to pancreatitis in mammals." (PMID 20109224, 2010). "NUPR1 was initially discovered in a rat model of pancreatitis, and subsequent studies have found that NUPR1 plays an important role in promoting tumorigenesis, tumour progression and even drug resistance." (PMID 40176685, 2025). "NUPR1 is a member of AT hook-containing chromosomal DNA-binding proteins that was first identified and cloned in a study of pancreatitis-induced tissue injury." (PMID 40421217, 2025). "Interestingly, NUPR1, a stress protein activated in pancreatitis, promotes fibrosis, inflammation, and cancer initiation and development, indicating that NUPR1 is essential for TME." (PMID 34067040, 2021). "Thus, we analyzed the effects of NUPR1 down-regulation on cell death induced by experimental pancreatitis in Nupr1-knockout (KO) and WT mice." (PMID 30451898, 2018). "Taken together, these results provide mechanistic insights into how Nupr1 cooperates with Kras to promote the development of pancreatic preneoplastic lesions by discovering and characterizing a role for this pancreatitis-inducible protein in modulating cellular senescence." (PMID 24902898, 2014). "NUPR1 (UniProtKB O60356), or nuclear protein 1, is an 82-residue-long (8 kDa), highly basic IDP, whose proper function is unknown, although it was first described as being activated in the exocrine pancreas in response to the cellular injury induced by pancreatitis." (PMID 34680086, 2021).
colorectal cancer (9 papers, 2021 to 2025). A primary or metastatic malignant neoplasm that affects the colon or rectum. "In particular, the downregulation of EPHB2 and LEFTY1 and upregulation of NUPR1 genes known to be associated with colorectal cancer were observed, suggesting their involvement in tumorigenic microenvironment." (PMID 39285481, 2024). "NUPR1 was characterized in colorectal cancers, where it exhibits high expression in the primary tumor stage." (PMID 39285481, 2024). "CRISPR-Cas9-mediated knockout of HERV-K (HML-2) env in DLD-1 colorectal cancer cells reduced migration, invasion, and tumor colonization and was sociated with nuclear protein-1 (NUPR1) reduction, indicating a potential connection." (PMID 36979914, 2023). "Previously, we reported that HERV-K env-related NUPR1 may activate the NUPR1 pathway in DLD-1 colorectal cancer cells through CRISPR-Cas9-mediated KO of HERV-K env." (PMID 37958549, 2023). "In support of this notion, ROS and the NUPR1 were decreased in HERV-K env knockout colorectal cancer, compared with the wild-type cells; however, HERV-K re-expression restored the elevated levels of both NUPR1 and ROS." (PMID 34359572, 2021). "As NUPR1 protein has been reported to be involved in ROS generation, apoptosis, autophagy, and ER stress, the effect of HERV-K env KO on these functions in DLD-1 colorectal cancer cells were analyzed." (PMID 33920455, 2021).